DRC5 (dynein regulatory complex subunit 5)
Description:
Component of the nexin-dynein regulatory complex (N-DRC) a key regulator of ciliary/flagellar motility which maintains the alignment and integrity of the distal axoneme and regulates microtubule sliding in motile axonemes. May play a role in the assembly of N-DRC. May be required for sperm motility.
Synonyms: TCTE1; D6S46; MGC33600; FAP155
Tractability: Small molecule: a structure with a bound ligand is known.
Gene: Protein-coding gene on chromosome 6 (44,278,734 to 44,297,698, reverse strand). Ensembl gene ENSG00000146221.
Subcellular location: Cell projection, cilium, flagellum; Cytoplasm, cytoskeleton, flagellum axoneme
Subcellular location (Human Protein Atlas): Mid piece; Vesicles; Cytosol
Gene Ontology:
Molecular function: protein binding
Biological process: cilium movement; flagellated sperm motility; microtubule-based movement
Cellular component: axonemal nexin link; axoneme; sperm flagellum; motile cilium
Genetic constraint (gnomAD): Loss-of-function variants: 32 observed, 35.31 expected, observed/expected ratio (o/e) 0.91, 90% interval 0.68 to 1.22. The upper end of that interval is the gene's LOEUF score, 1.22, which puts it in group 5 of 6, group 1 being the genes least tolerant of losing a copy. Missense variants: 625 observed, 677.76 expected, observed/expected ratio (o/e) 0.92, 90% interval 0.86 to 0.99. Synonymous variants: 239 observed, 284.79 expected, observed/expected ratio (o/e) 0.84, 90% interval 0.75 to 0.93.
Homologues: Orthologues: chimpanzee TCTE1 (99% identical), macaque TCTE1 (97% identical), dog TCTE1 (85% identical), pig TCTE1 (84% identical), rabbit TCTE1 (81% identical), mouse Tcte1 (77% identical), rat Tcte1 (76% identical), guinea pig TCTE1 (75% identical), tropical clawed frog tcte1 (50% identical), zebrafish tcte1 (47% identical), Drosophila melanogaster CG14325 (24% identical).
Diseases named in the same sentence as DRC5 in open-access papers:
DRC5 is named in the same sentence as 10 diseases in open-access papers, as found by Europe PMC text mining. Sharing a sentence is not in itself a finding about the gene and the disease.
DRC5 shares sentences with these, for which no sentence is quoted: asthenozoospermia (4 papers); Azoospermia (1); Bell's palsy (1); cancer (1); Ciliopathies (1); Cryptozoospermia (1); infertile (1); male infertility (1); oligoasthenoteratozoospermia (1); sterility (1).